CCND1 (cyclin D1)
Diseases named in the same sentence as CCND1 in open-access papers (continued):
Sharing a sentence is not in itself a finding about the gene and the disease.
tumor (continued). "Other compounds, as fucoidan and sulfated galactofucan have been shown to reduce tumor growth and inhibit tumor angiogenesis, in part through the inhibition of STAT3-regulated genes, as VEGF, Bcl-xL, and cyclin D1." (PMID 33916438, 2021). "Since the intracellular content of cyclin D1 is a determinant for tumorigenesis in certain types of tumors, cyclin D1 has been used as an index in the exploration of USP2 inhibitors as anti-tumor drugs." (PMID 33530560, 2021). "Transactivated β-catenin forms a complex with T-cell factor/lymphoid enhancer-binding factor family members and induces many instrumental downstream genes, such as CCND1 and MYC, which promote tumour development." (PMID 34155197, 2021). "Because this signaling impacts on the cell cycle, cyclin-D1/CDK4 and CDK6 function, autophagy and IR are involved in many human neoplasms." (PMID 34445095, 2021). "Reduced APC expression increases the expression of β-catenin and β-catenin-mediated cyclin D1, c-Myc, and PKM2 expression, thereby leading to enhanced aerobic glycolysis, ESCC cell proliferation, and tumour formation in mice." (PMID 34155197, 2021). "STAT3 acts astranscriptional regulator of a variety of tumor-promoting genes such asVEGF, c-MYC, CCND1 (cyclinD1), BIRC5 (survivin), which are involved in tumor development andprogression." (PMID 33749701, 2021). "For the “Pathway in cancer” pathway, a total of 18 risk lncRNAs synergistically regulated ER (ESR1), E2F (E2F1 and E2F2), CyclinA1 (CCND1), and Survivin (BIRC5), which indirectly leads to tumor cell proliferation." (PMID 34149805, 2021). "The diagnosis of MCL was confirmed by the expression of CD20, CD5, cyclin D1, SOX11, and SAMHD1 of tumor cells." (PMID 34976810, 2021). "The expression levels of cyclin D1 and cyclin D3 were suppressed in the DHA treatment group, suggesting a G1 phase arrest induced by DHA on tumor cells." (PMID 33995655, 2021). "miR-15a and miR-16 act as tumor suppressors: they downregulate multiple oncogenes (BCL2, MCL1, CCND1, and WNT3A), decreasing PC cell survival, proliferation, invasion, and EMT by targeting TGF-β signaling." (PMID 34830196, 2021). "Palbociclib inhibited endothelial cell proliferation and tumor angiogenesis by disrupting the CDK4/6–cyclin D complex, thus the miR200b/QKI/CCND1 axis." (PMID 34439268, 2021). "Moreover, miR-720 could directly target CCND1 as a tumor suppressor for the treatment of PC." (PMID 33996561, 2021). "To test whether the observed up-regulation of DNMT1 expression in ALK tumor samples is associated with deregulation of cell cycle–associated genes, we performed Western blot analysis using antibodies against c-MYC, CDK4/CDK6, cyclin D1, and the proliferation marker PCNA." (PMID 33310759, 2021). "In turn, Wu and colleagues (2014) confirmed the tumor growth inhibition after RSV intravesical treatment due to STAT3 signaling pathway inhibition (reduced expression of survivin, cyclin D1, c-Myc and VEGF)." (PMID 34360552, 2021). "We found tumor tissues with high FAM83B expression had high BCL2 and CCND1 expression, and had low apoptosis inhibitor XIAP expression." (PMID 33423038, 2021). "The treated tumor showed several CNVs in driver genes, including amplifications in MCL1, TERT, CCND1, AKT1, MYC, EGFR, and FGFR3; deletions in CDK1B, CDKN2A and CDKN2B; a PIK3CA hotspot mutation; and a high TMB." (PMID 34680239, 2021). "A Lung-MAP trial (SWOG S1400) demonstrated the amplification of CDK4 or CCND1/2/3 in patients with squamous NSCLC and tumor." (PMID 34395246, 2021). "Key regulators of cell-cycle progression and inflammation, including Cyclin D1, Cyclin D2, COX-2 were shown to be favorably modulated by Anthos, with the most dramatic reductions in expression observed in tumor tissue samples." (PMID 34926717, 2021).
tumor (continued). "Consistently, immunohistochemical staining of specimens from in vivo tumor nodules demonstrated that the protein levels of p-ERK1/2, β-catenin, cyclin D1, c-Myc, and N-cadherin were diminished, and the protein level of E-cadherin was increased by SHP-1." (PMID 34591414, 2021). "The western blotting assays of tumor tissue lysates showed that TSN inhibited the PI3K/Akt/mTOR signaling pathway and the expression of MMP-2, cyclin D1, and Bcl-2 proteins." (PMID 34530814, 2021). "Deficiency of YTHDF1 functionally prevents NSCLC cell proliferation and tumor formation through inhibiting the translational efficiency of cyclin-dependent kinase 2 (CDK2), cyclin-dependent kinase 4 (CDK4), and cyclin D1 (CCND1)." (PMID 34359836, 2021). "The majority of the tumor cells were positive for CDK4 staining and cyclin D1 staining in the nuclei." (PMID 34395284, 2021). "In transplanted tumor tissue, in comparison with control groups, WNT1, Cyclin D1, and c-myc mRNA expression was decreased in mimics group." (PMID 34657551, 2021). "Depletion of PRMT2 expression leads to an increase in estrogen-induced CCND1 expression and promotion of cell proliferation and colony formation, indicating That PRMT2 has tumor-suppressive activity." (PMID 34006904, 2021). "Compared with the NC tumours, the protein level of CD11b and CD14 greatly increased in ZEB1 knock‐down tumours, while the expression of cyclin D1, cyclin A2, p‐Rb and CDK4 was markedly decreased in ZEB1 knock‐down tumours." (PMID 33960640, 2021). "The results of the present study show that compared to Avastin treatment alone, combination treatment with FO and Se exerted a greater decrease in nuclear cyclin D1/E and CDK-2,4,-6 in TNBC tumor tissues." (PMID 33805447, 2021). "Undoubtedly, the well-described effects of MYC on global transcription and protein production, CCND1 on cell cycle transition, and KIF18A on chromatin segregation contribute greatly to YAP-mediated in vivo tumor expansion." (PMID 33514403, 2021). "The overexpression of HOPX, upregulation of p21, and downregulation of cyclin D1 and CDK4 regulate the progress of migration and invasion of MDA-MB-468 cells to modulate tumor growth of the breast." (PMID 34235216, 2021). "Meanwhile, the expression of CCNA2 and CCNB1 was positively correlated with tumor-killing immune cells, such as CD8+ T cells.The copy numbers of CCNA2, CCNB1, CCND1, CCNE1, and CCNF was positively related to gene expression." (PMID 33996604, 2021). "The weight and volume of tumour tissue in SC66‐treated nude mice were significantly reduced, and the expression level of cyclin D1 was significantly downregulated." (PMID 34687144, 2021). "Among MMRp CRCs, we found MYC and FLT3 amplification in one tumor (T32), MYC and CCND1 amplification in 1 tumor (T36), and EGFR amplification in one tumor (T38)." (PMID 33435234, 2021). "When activated, expression of downstream target genes such as cyclin D1 and c-MYC are upregulated, leading to promotion of tumor cell proliferation, invasion and migration." (PMID 33123284, 2020). "Significant copy number alterations of CCND1 and EGFR correlate with clinical stage, tumor differentiation, and lymph node metastasis in oral squamous cell carcinoma (OSCC)." (PMID 33317149, 2020). "In summary, we have shown that GAS7, a direct downstream target of miR-362-5p, can exert its tumor suppressive functions in THP-1 cells through regulation of PCNA, CDK4, cyclin D1, and p21." (PMID 31925702, 2020). "Previous studies also suggested a functional link between ER stress response and tumor dormancy, which was supported by the findings that PERK activation inhibited cyclin D1 synthesis for G1 arrest, and that ATF6 was constitutively active in dormant cells." (PMID 33396303, 2020).
tumor (continued). "Knocking down HMGN5 decreased the expression of Bcl-2, Cyclin D1, MMP-2, and MMP-9 and increased the expression of Bax and p21 which is related to the malignant phenotype of tumor proliferation, migration, and invasion." (PMID 32596388, 2020). "Subsequent in vivo studies establish that the Cyclin D1/CDK4 axis plays a critical role not only in glial tumor cells but also in stromal-derived cells, which sustain tumor growth." (PMID 33317149, 2020). "In agreement with previous findings, we found that ATP6AP2 expression is higher in tumor tissues than that in normal tissues, moreover, level of ATP6AP2 expression in GBM is positively correlated with those of CTNNB1, CCND1 and AGT." (PMID 32143717, 2020). "Cyclin D1 (CCND1) has been revealed as a key regulating protein in cell cycle (G1 phase) and plays a critical role in promoting tumor development." (PMID 32566661, 2020). "In this study, DDP also delayed tumour growth in LC mice with PCBS syndrome and downregulated the STAT3, p-STAT3, and cyclin D1 protein expression levels to some extent." (PMID 32382281, 2020). "The expression of CCND1 and CCNA1 was even more prominently elevated in the tumor region than in the non-tumor tissues in Atg7ΔHep mice." (PMID 32382012, 2020). "Roniciclib binds to and inhibits the activity of CDK1/Cyclin B, CDK2/Cyclin E, CDK4/Cyclin D1, CDK6/Cyclin D3, and CDK9/Cyclin T1, which are serine/threonine kinases playing key roles in the regulation of tumor cell proliferation and survival." (PMID 32737364, 2020). "In the primary tumor, 15 (35.7%), 11 (26.2%), 4 (9.5%) and 4 (9.5%) patients harbored amplifications in all 3 exons of MYC, CCND1, ERBB2 and CCNE1, respectively." (PMID 33298978, 2020). "Collectively, these results indicate that GSK3β-mediated regulation of cell cycle progression via cyclin D1, CDK4 and cyclin B1 is responsible for tumor cell survival and proliferation in ESCC." (PMID 32678196, 2020). "Depletion of circ‐CCND1 significantly inhibited LSCC cell proliferation in vitro and retarded tumour growth in vivo." (PMID 31951319, 2020). "SLPI also plays an important role in the regulation of cell cycle progression by promoting the expression of cyclin D1 and IGFBP-3 in tumor cells." (PMID 32742768, 2020). "HIF-1α promotes tumor cell growth, migration, and invasion in OS through activation of the AKT/cyclin D1 signal cascade." (PMID 33425993, 2020). "As expected, our data showed that δ‐catenin knockdown suppressed β‐catenin nuclear localization and subsequent alteration of Bcl2L1 and cyclin D1 level in both ACHN cells and ACHN‐derived xenograft tumor tissue." (PMID 31991069, 2020). "The overexpression of oncogenic proteins, such as Cyclin-D1, MCL-1, C-FLIP, XIAP, MMP-9, MMP-2, uPA, and VEGF, are correlated with constitutive NF-κB activity and involved in promoting tumor progression in CRC." (PMID 32429376, 2020). "Some other cyclin family members, such as cyclin-dependent kinase 4 or cyclin D1 (CCND1), also mediated pathological process in tumor cells and motivated cellular metastasis and tumor invasiveness." (PMID 33628185, 2020). "NF-κB has been shown to control the expression of tumor-related genes, such as Cyclin D1, c-Myc, HER2, interleukins, and XIAP, to regulate chronic inflammation, tumor cell survival, antiapoptosis, proliferation, invasion, and angiogenesis." (PMID 33282634, 2020). "Western blot analysis of xenograft tumor tissues confirmed a strong MTA1, Cyclin D1 and Notch 2 downregulation upon treatment with compounds compared to control vehicle-treated tissues." (PMID 33255879, 2020). "Although the EGFR and CCND1 (cyclin D1) loci were triploid, and the MET locus was triploid with LOH, the transcriptome analysis showed only MET RNA overexpression in this tumor, contrasting with the findings from F8." (PMID 31963394, 2020). "Consistently, we observed decreased cyclin D1 and CDK4 levels and delayed cell growth in UCHL5 knocked down tumor cells." (PMID 33046988, 2020).
tumor (continued). "Studies have shown that G6PDH promotes tumor cell proliferation mainly via ROS-stimulated p-STAT3 signaling activation and upregulation of cyclin D1 expression in RCC cells." (PMID 33123534, 2020). "Serial sections and immunohistochemical (IHC) staining showed that tumor tissues injected with circ5615 ASO had fewer TNKS, β-catenin, and CCND1-positive cells." (PMID 32393760, 2020). "This combination inhibits RB hyperphosphorylation by inhibiting the cyclin D1/CDK4/CDK6 complex, inducing cell cycle arrest and inhibiting tumor growth." (PMID 32508030, 2020). "Of these, let-7f is a member of the let-7 family, which includes well-known tumor-suppressor miRNAs that target oncogenes, such as MYC, RAS, and CCND1." (PMID 32674274, 2020). "Knockdown of BAP18 decreased MYC, CCND1, KCNK5, and FOXC1 mRNA expression in xenograft tumor tissue." (PMID 32986841, 2020). "Genomic profiling showed that CCND1 amplification was present in 57% tumor tissue and often coordinated with EGFR amplification to accelerate tumor progression." (PMID 32190688, 2020). "Introduction of CYCLIN D1 or MYCN overcomes this PAX-FOXO1-mediated cell cycle inhibition and promotes tumour growth." (PMID 33175861, 2020). "In accordance with these findings, the tumor cells from the knockout mice had a higher expression of the proliferation markers PCNA, Cyclin D1 and CDK4." (PMID 33245729, 2020). "Collectively, we hold the opinion that miR-93 exhibited a tumor suppressor role by targeting E2F1 and CCND1, thereby inactivation of pRB/E2F1 pathway and AKT phosphorylation." (PMID 32796817, 2020). "miR-15a/16 exerts tumor suppressive roles by targeting multiple oncogenes, including BCL2, TWIST1, MCL1, CCND1 and WNT3A." (PMID 32678069, 2020). "E2F8 overexpression in HCC facilitated the tumor occurrence and aggressiveness through activating a E2F1/Cyclin D1 signaling pathway to regulate the G1-S transition or transcriptionally suppressing CDK1 to induce hepatocyte polyploidization." (PMID 31990034, 2020). "Analyzing tumor tissue lysates by western blots demonstrated that BRD4-regulate proteins (Bcl-2, Myc, cyclin D1) were significantly downregulated in I-BET726-treated A431 tumor tissues." (PMID 32371868, 2020). "Wnt-related targets, including c-Myc, cyclin D1, MMP-7, and VEGF, are critical contributors to tumor cell proliferation, invasion, and migratory potential." (PMID 32807788, 2020). "Western blotting showed that E2F4 knockdown promoted the expression of CD11b and CD14 and inhibited the expression of cyclin D1, cyclin A2, P‐Rb and CDK4 compared with the expression in control tumours." (PMID 31943751, 2020). "The levels of eight hub genes expression (FN1, CCND1, CDH2, CXCL12, MET, IRS1, DCN and FMOD) in PTC and para-cancerous non-tumor tissues were detected by qRT-PCR." (PMID 32714651, 2020). "To further elucidate the effect of EHD on the STAT3/cyclin D1 signalling pathway, we analysed the STAT3 and cyclin D1 levels in xenograft tumours in nude mice by immunohistochemistry analyses." (PMID 32382281, 2020). "Cyclin D1 and CDK4/6 play a crucial role in G1/S cell cycle progression by phosphorylating and inactivating the Rb, a tumor suppressor that restrains G1/S cell cycle transition." (PMID 33139730, 2020). "We found that BACE2 knockdown led to significantly decreased levels of p‐p65 and key tumour promoters, namely CDK2, CDK4, cyclin D1 and c‐Myc." (PMID 31856384, 2020). "We analyzed CDK4, CDK6, cyclin A, cyclin D1, ATF4, and CHOP protein levels in excised tumor sections from saline- and CPX-treated groups." (PMID 32719342, 2020). "Several studies have showed that Prdx1 promotes tumor occurrence mainly by adjusting the levels of ROS, TGF-β1, mTOR/p70S6K, and ROS/ERK/cyclin D1." (PMID 32357862, 2020).
tumor (continued). "As cell cycle regulators, CCND1 and CDK4 play critical roles in regulating the cell cycle of normal and tumor cells." (PMID 32742488, 2020). "Mouse tumor tissues were sectioned and subjected to immunohistochemical staining to analyze the expression of class I HDACs and p21, CDK4, cyclin D1, Ki-67, and EMT-related genes." (PMID 32850418, 2020). "Cyclin D1 also contributes to inactivation of tumor suppressor protein, retinoblastoma protein, in a CDK-dependent manner that can enhance tumor progression." (PMID 32405344, 2020). "We demonstrated that the GOLPH3-STIP1 interaction regulates hTERT expression via c-Myc, and then affects cell cycle-related signaling including cyclin D1 leading to the promotion of PDAC proliferation and tumor growth." (PMID 33134174, 2020). "The let-7 family members, widely viewed as tumor suppressor microRNAs (targeting multiple oncogenes such as HMGA2, c-Myc, RAS, and cyclin D1), are frequently reduced in cancer, which correlates with increased tumorigenicity and poor prognosis." (PMID 32560271, 2020). "Taken together, here we demonstrate for the first time that all three ERs- ERα, ERβ and GPR30 are expressed in human A431 cSCC cells and further ER agonist based activation modulates the expression of tumor markers CD55 and Cyclin D1." (PMID 31611744, 2019). "A study of NPC tumor specimens found that tumor-suppressing protein PDCD4 suppresses the pPI3K/pAKT/c-JUN signaling pathway, which in turn modulates miR-374a's binding to CCND1, resulting in dysregulation of NPC cell growth, metastasis, and chemoresistance." (PMID 31456943, 2019). "In agreement with up‐regulation, down‐regulation of RN181 significantly decreased the expression of p21 but increased the expression of cyclin D1 and CDK4 in xenograft tumours of AGS cells (AGS‐KD versus AGS‐NC control, all p < 0.05)." (PMID 30714150, 2019). "Western blot data showed that the protein levels of PCNA, CDK4, CDK6, Cyclin D1, MMP-2, MMP-9, and Bcl-2 were decreased, but cleaved caspase-3 was increased in tumor tissues of ApoE KO mice compared to those of WT mice." (PMID 31275318, 2019). "In line with tumor mRNA analysis, SMARCA4 IHC-negative NSCLC tumors (n = 11) expressed lower levels of cyclin D1 compared to SMARCA4 IHC-positive NSCLCs (n = 82) although not statistically significant (p = 0.105)." (PMID 30718506, 2019). "We found ten potential prognostic genes, including eight tumor suppressor and/or driver genes (VEGFA, CCND1, BAX, IL7R, SHC1, FLT1, IL7, and JAK3), as well as two chemokines (CXCL9 and CXCL10)." (PMID 31661791, 2019). "Either Sal-B or cisplatin treatment decreased tumor tissue levels of tumor necrosis factor (TNF-α), matrix metalloproteinase-8 (MMP-8), and Cyclin D1 in ESC treated mice." (PMID 31726654, 2019). "In a previous study, we noted the overexpression of CCND1 protein in 37% of OSCC cases and found that this was correlated with tumor differentiation, LNM, and poor clinical outcomes." (PMID 31159251, 2019). "ER subtype agonist based activation on A431 cells was performed to investigate their role in modulating mRNA and protein expression of tumor markers CD55 and Cyclin D1." (PMID 31611744, 2019). "ISA-2011B not only strongly inhibited tumor growth, but also significantly lowered expression of phosphorylated AKT and its downstream effectors such as cyclin D1, VEGF, VEGFR1 and VEGFR2." (PMID 30104711, 2019). "ES cells consequently have an activated cyclin D1/CDK4 pathway and require CDK4 and cyclin D1 for growth.In vivo data demonstrated decreased tumor growth and prolonged survival with CDK4/6 inhibition." (PMID 31031965, 2019).